CP (ceruloplasmin)
Diseases named in the same sentence as CP in open-access papers (continued):
Sharing a sentence is not in itself a finding about the gene and the disease.
aceruloplasminemia (continued). "Aceruloplasminemia (ACP) (OMIM#604290, ORPHA48818) is an adult-onset rare autosomal recessive disorder due to mutations in the CP gene (3q24-q25) encoding ceruloplasmin (CP), a copper-containing ferroxidase involved in maintaining iron homeostasis." (PMID 32235485, 2020). "Aceruloplasminemia (ACP) is a rare, adult-onset, autosomal recessive disorder, characterized by systemic iron overload due to mutations in the Ceruloplasmin gene (CP), which in turn lead to absence or strong reduction of CP activity." (PMID 31024241, 2019). "We investigated the potential of ceruloplasmin replacement therapy in reducing the neurological pathology in the ceruloplasmin‐knockout (CpKO) mouse model of aceruloplasminemia." (PMID 29183916, 2018). "Mice that model human aceruloplasminemia through knockout of ceruloplasmin (Cp) and hephaestin (Hp), its homolog, have been studied, showing progressive retinal degeneration." (PMID 30360383, 2018). "Patients with biallelic mutations in the ceruloplasmin gene located on 3q (not 13q of WD) develop aceruloplasminemia, a very rare neurodegenerative disorder associated with abnormal iron metabolism, anemia, and diabetes." (PMID 40197188, 2025). "Biologically, aceruloplasminemia is associated with low serum copper, absent ceruloplasmin, and high ferritin concentrations." (PMID 38355710, 2024). "Furthermore, recombinant human CP would represent a virtually unlimited source of protein available to test the validity of enzyme replacement therapy for treatment of aceruloplasminemia patients." (PMID 34360993, 2021). "Aceruloplasminemia (OMIM #604290) is a severe adult-onset form of Neurodegeneration with Brain Iron Accumulation (NBIA), caused by homozygous or compound heterozygous mutations in the ceruloplasmin (CP) gene." (PMID 33839643, 2021). "When ceruloplasmin activity is impaired (hypoceruloplasminemia) or absent (aceruloplasminemia) due to such genetic variants, marked iron overload ultimately develops as a result of cellular iron retention." (PMID 34067164, 2021). "Here, we describe the largest series of non-Japanese patients with aceruloplasminemia published so far, including 13 individuals from 11 families carrying 13 mutations in the CP gene (7 missense, 3 frameshifts, and 3 splicing mutations), 10 of which are novel." (PMID 32235485, 2020). "Decreased serum ceruloplasmin may aggravate iron accumulation in WD, which is similar to the pathogenesis of aceruloplasminemia." (PMID 33041766, 2020). "Even though forms of hypoceruloplasminemia, with partial ceruloplasmin expression, were known earlier, the first case of aceruloplasminemia was reported in a 52-years old Japanese female presenting with blepharospasm, retinal degeneration and diabetes mellitus." (PMID 30420953, 2018). "Cp−/− mice bearing targeted disruption of ceruloplasmin represent a model of aceruloplasminemia." (PMID 30420953, 2018). "Aceruloplasminemia is a rare genetic disorder of ceruloplasmin dysfunction that results in an iron retention within various tissues that can be recapitulated in ceruloplasmin knockout mice." (PMID 24527451, 2014). "Moreover, impairment of ceruloplasmin ferroxidase activity in the course of Wilson’s disease (WD), leading to the accumulation of ferrous ions just like what is expected in aceruloplasminemia, is another known reason for iron overload accompanied by chronic liver disease." (PMID 39050104, 2024). "Furthermore, recombinant CP could be evaluated for enzyme replacement therapy for the treatment of aceruloplasminemia." (PMID 34360993, 2021). "Aceruloplasminemia is caused by mutations in CP gene leading to absent or dysfunctional protein." (PMID 29183916, 2018). "Here, it is pertinent to recapitulate clinical and neuropathological findings in aceruloplasminemia, a rare hereditary disorder caused by mutation in the CP gene and characterized by absent serum CP activity with Fe deposition in the brain leading to neuropsychiatric symptoms." (PMID 27530256, 2016).
aceruloplasminemia (continued). "However, two NBIA diseases, hereditary ferritinopathy and aceruloplasminemia, caused by mutations in the ferritin-L subunit gene (FTL) and in the ceruloplasmin (CP) gene, respectively, suggest that abnormal iron metabolism is the pathologic event leading to neurodegeneration in these disorders." (PMID 24896637, 2014). "In fact, only the simultaneous ablation of CP and hephaestin (HEPH) genes in mice is able to recapitulate symptoms consistent with those shown by aceruloplasminemia patients, suggesting that hephaestin can compensate the lack of CP in mice, but not in humans." (PMID 30744104, 2019). "Activity of CP is clearly important for retinal health, as patients with the autosomal recessive disease aceruloplasminemia (no ceruloplasmin) have degenerative changes in the peripheral or macular RPE, in addition to a Parkinson's-like neurodegeneration." (PMID 37439255, 2023). "This has been shown in several studies after CP immuno-depletion and in humans with aceruloplasminemia with no NO oxidase activity." (PMID 33096845, 2020). "Unexplained anemia with low transferrin saturation and high ferritin levels without inflammation should prompt the suspicion of aceruloplasminemia, which can be easily confirmed by low serum ceruloplasmin levels." (PMID 32235485, 2020). "The combination of low serum iron and peripheral tissue iron overload in aceruloplasminemia is similar to that observed in ferroportin disease and can be explained by the defective iron mobilization from tissue macrophages due to lack of ceruloplasmin." (PMID 30420953, 2018). "In the brain ceruloplasmin is important as a binder of iron, and in the absence of ceruloplasmin (aceruloplasminemia), iron is able to induce tissue injury by increasing lipid peroxidation." (PMID 19159481, 2009).
Wilson disease (60 papers, 2007 to 2026). A very rare inherited multisystemic disease presenting non-specific neurological, hepatic, psychiatric or osseo-muscular manifestations due to excessive copper deposition in the body. "Wilson’s disease was a concern due to the patient’s low ceruloplasmin of 0.09 g/L being within the diagnostic range for Wilson’s disease (<0.20 g/L)." (PMID 40895663, 2025). "Ceruloplasmin mutations cause Wilson’s disease, while FTL mutations cause neuroferritinopathy, both of which are characterized by basal ganglia degeneration and severe movement disorders, including parkinsonism." (PMID 39164482, 2025). "Congenital or genetic causes of preceding liver disease include Wilson's disease and hemochromatosis which can be evaluated by specialized genetic testing or through initial screening with serum ceruloplasmin and ferritin, respectively." (PMID 40134944, 2025). "The reduction of circulating holo-CP concentrations is one of the early symptoms of Wilson’s disease caused by the impaired transfer of copper via ATP7B to CP and concomitant hepatic copper accumulation." (PMID 37311819, 2023). "The serum concentration of fetuin-A is a sensitive marker of liver cirrhosis in Wilson’s disease, independently of the H1069Q mutation, ceruloplasmin concentration or systemic inflammation." (PMID 36881584, 2023). "Our results indicate that the serum concentration of fetuin-A is a sensitive marker of liver cirrhosis in Wilson’s disease, independently of the H1069Q mutation, ceruloplasmin concentration or systemic inflammation." (PMID 36881584, 2023). "Scheinberg and Gitlin first described Wilson’s disease in 1952 after noting a deficiency of ceruloplasmin in affected individuals’ serum, a diagnostic test that remains important today." (PMID 37629187, 2023). "Wilson’s disease (WD) is a hereditary disorder of copper metabolism, producing abnormally high levels of non-ceruloplasmin-bound copper, the determinant of the pathogenic process causing brain and hepatic damage and dysfunction." (PMID 36012580, 2022). "Mutation of a copper transporter in Wilson's disease causes decreased serum ceruloplasmin levels resulting from failure of copper incorporation into ceruloplasmin." (PMID 23825457, 2013). "In fact, decreased CP plasma levels due to impairment of CP copper loading is eminently demonstrated in Wilson disease, where variants in the copper loading transporter ATP7b result in the expression of an incorrectly folded CP and its rapid degradation (e.g., see70)." (PMID 40043514, 2025). "In our report, we describe the case of a patient with aceruloplasminaemia, which was identified in an early, neurologically asymptomatic stage while searching for the cause of chronic hepatopathy with low values of serum ceruloplasmin with originally supposed Wilson’s disease." (PMID 32264837, 2020). "Protein levels of the human ortholog of CP are elevated in patients with schizophrenia, a related mental health disorder, and patients with Wilson’s Disease, a genetic disorder caused by dysfunction of an enzyme upstream of ceruloplasmin, have a higher incidence of BSDs than the general population." (PMID 29768498, 2018). "Wilson’s disease (WD) is a copper metabolism disorder due to mutations of the ATP7B gene encoding for a hepatocyte copper carrier that induces an inability of the liver cell to evacuate copper as well as a significant decrease in the synthesis of circulating ceruloplasmin." (PMID 37563694, 2023). "Laboratory investigations should include screening for viral hepatitis (HAV, HBV, and HCV), autoimmune liver diseases (ANA, ASMA, and LKM1 antibodies), and Wilson's disease (serum ceruloplasmin)." (PMID 40546311, 2025). "Wilson’s disease was considered due to a low ceruloplasmin level at 0.09 g/L (normal = 0.2-0.6 g/L) and an elevated 24-hour urinary copper of 40 μg (normal = 3-35 μg)." (PMID 40895663, 2025).
Wilson disease (continued). "Low serum CP is also seen in Wilson disease, Menkes disease, hypoproteinemia, and even asymptomatic ACP heterozygotes." (PMID 40729217, 2024). "We reviewed a female patient hospitalized in 2023 with clinical manifestations of elevated aminotransferases and decreased ceruloplasmin, as well as genetic testing for an initial diagnosis of Wilson’s disease." (PMID 38273263, 2024). "Another study found that male patients with Wilson's disease exhibited low serum ceruloplasmin accompanied by high serum ferritin levels." (PMID 36819130, 2023). "Wilson's disease is an autosomal recessive inherited disease with congenital copper metabolism disorder, characterized by decreased ceruloplasmin and increased urine copper, which can involve multiple organs." (PMID 36381061, 2022). "Mutations of the ATP7B gene result in low holo-ceruloplasmin levels, as exemplified in Wilson’s disease, which is the paradigmatic disease of non-ceruloplasmin copper toxicosis or accumulation in both the liver and brain." (PMID 36139084, 2022). "Wilson disease is characterized by copper metabolism disorder caused by the mutations of ATP7B gene, manifested as decreased ceruloplasmin and increased urine copper, which can simultaneously or solely involve the liver, eyes, and nervous system." (PMID 36381061, 2022). "Wilson's disease (WD) is an autosomal recessive inherited disorder characterized by low ceruloplasmin serum levels and copper accumulation, particularly in the liver and brain." (PMID 35251368, 2022). "Serum levels of non-ceruloplasmin-bound copper of AD patients were also similar to those of nine Wilson’s disease patients, although Wilson’s disease patients had lower levels of total copper and ceruloplasmin-bound copper than AD patients." (PMID 31832729, 2020). "Regarding the low level of immunoreactive CP (measured by immune nephelometry) concentration (0.02 g/l), Wilson’s disease was suspected." (PMID 32264837, 2020). "Patients with Wilson’s disease have extremely low levels of ceruloplasmin, which binds to copper, resulting in low serum copper concentrations, but high copper concentrations in urine and tissues." (PMID 28797287, 2017). "The symptoms of Wilson's disease, that is characterized by low levels of ceruloplasmin with subsequent copper deposition in various tissues including brain, often mimic those of schizophrenia." (PMID 19017404, 2008). "Phenotypic analyses included age of onset, clinical subtype, Kayser-Fleischer ring (KFR), copper metabolism profiles (serum copper [SCu], serum copper oxidase [SCO], ceruloplasmin [CP]), Unified Wilson’s Disease Rating Scale Part I (UWDRS-I), and Child-Turcotte-Pugh (CTP) scores." (PMID 41691313, 2026). "In clinical practice, PA is primarily used to treat copper metabolism disorders and is a key medication for managing conditions such as Wilson’s disease (WD), exerting systemic effects through high-affinity binding to non-ceruloplasmin-bound copper in the plasma." (PMID 40969742, 2025). "In addition, it has a correlation with neurodegenerative diseases such as AD, Parkinson’s disease, and Wilson’s disease, as these disorders exhibit alterations in the metabolism of metal ions, accumulation of iron in the brain, and decreased activity of CP." (PMID 38890712, 2024). "Because CP is an acute phase protein, it may also be within the normal range in patients with Wilson’s disease during inflammation." (PMID 37296680, 2023). "Wilson ATPase plays an essential role in transporting copper to secretory pathways of hepatocytes; impaired movement into these compartments results in the disruption of ceruloplasmin production, leading to significant drops in serum ceruloplasmin levels due to Wilson’s disease." (PMID 37629187, 2023). "Finally, Wilson’s disease was confirmed because of an elevated 24 h urinary copper excretion and abnormally low serum levels of copper and ceruloplasmin." (PMID 36291607, 2022).
Wilson disease (continued). "Wilson disease (WD) is caused by copper overload mainly in the liver and brain as a consequence of mutations affecting the P-type ATPase transporter responsible for copper excretion into the biliary system and ceruloplasmin maturation through the trans-Golgi network." (PMID 31779102, 2019). "Ceruloplasmin apoprotein is excessively secreted by hepatocytes in the presence of copper incorporation impairment, because of a dysfunction of the copper–transporting ATPase 7b, as it occurs in Wilson’s disease." (PMID 19690651, 2007). "Wilson disease is an autosomal recessive disorder of copper transport and is characterized by excessive accumulation of cellular copper in the liver and other tissues because of impaired biliary copper excretion and disturbed incorporation of copper into ceruloplasmin." (PMID 29540233, 2018). "Accordingly, SELENOP levels are relatively low in serum of patients with Wilson’s disease and LPP rats, especially in those with low CP concentrations." (PMID 37311819, 2023). "Mutation in the ATP7B gene results in disturbances in copper binding to ceruloplasmin (CP) by the ATP7B protein and leads to copper accumulation in the liver up to the toxic level in patients with Wilson disease." (PMID 33260507, 2020). "Iron accumulation is not generally a major feature of Wilson disease just due to a low ceruloplasmin level, because most patients do have some circulating level of oxidase-active ceruloplasmin." (PMID 38731973, 2024). "Other laboratory parameters in patients with Wilson disease were abnormal, including serum ceruloplasmin < 0.2 g/L, non-ceruloplasmin-bound serum copper > 25 μg/L, urinary copper excretion > 1.6 μmol/24 h, and liver copper > 250 μg/g dry wt." (PMID 38731973, 2024). "ICC, however, was not considered to be a straightforward early onset of Wilson disease because ceruloplasmin was consistently normal, and both clinical and histologic recovery was maintained in the long-term despite the withdrawal of D-penicillamine therapy." (PMID 38731973, 2024). "Liver diseases such as intrahepatic cholestasis, biliary atresia and Wilson’s disease were excluded because the five patients had normal levels of serum γ-glutamyltransferase (GGT), muscle creatine phosphokinase (CPK), bilirubin, bile acid, and ceruloplasmin." (PMID 35145548, 2022). "The absence of metallothionein (Wilson's disease) can result in the decrease of serum ceruloplasmin levels, leading to the accumulation of Cu in the liver, kidneys, skin, brain (with associated neurological symptoms)." (PMID 36063463, 2022). "There is no definitive test for Wilson's disease but the presence of Kayser Fleischer rings, low copper ceruloplasmin levels, high urine copper, and high copper content on liver biopsy are all highly suggestive of the condition." (PMID 26136783, 2015). "Serum ceruloplasmin, serum iron, total iron binding capacity were investigated, and metabolic liver diseases such as hemochromatosis or Wilson disease were ruled out." (PMID 24159391, 2013). "The patient was evaluated for viral infections (negative serologies), autoimmune liver disease (no hypergammaglobulinemia, normal IgG, negative autoantibodies), Wilson disease (normal ceruloplasmin), coeliac disease (negative anti-TTG Ab), and metabolic diseases." (PMID 39650963, 2024). "Interestingly, that strong restriction of copper intake by Golgi complex leads to the same phenotype as in patients with Wilson disease, which develops from mutations in the ATP7B gene, but not in ceruloplasmin gene." (PMID 30959888, 2019). "In addition, the level of ceruloplasmin was normal, which did not support a diagnosis of Wilson’s disease." (PMID 28344651, 2017). "Wilson's disease (WD), also known as hepatolenticular degeneration, is an autosomal recessive inherited disease that is caused by a mutation in the ATP7B gene and is characterized by impaired biliary copper excretion and lack of ceruloplasmin synthesis." (PMID 25375371, 2014).
Wilson disease (continued). "Similarly, psychotic symptoms occur in Wilson's disease, in which there is copper deposition in liver, cornea, and brain due to lack of ceruloplasmin." (PMID 19017404, 2008).